HGF (hepatocyte growth factor)
Diseases named in the same sentence as HGF in open-access papers (continued):
Sharing a sentence is not in itself a finding about the gene and the disease.
tumor (continued). "CAFs have also been shown to drive tumor cell proliferation, migration and invasion by producing high amounts of mitogenic factors, hepatocyte growth factor (HGF) and FGF." (PMID 30103384, 2018). "In a study using mouse xenograft models, emibetuzumab blocked both HGF-dependent and -independent tumor growth." (PMID 30134579, 2018). "In such conditions, the HGF secreted by the reactive tumor stroma acts on cancer cells expressing MET to promote pro-invasive and anti-apoptotic responses." (PMID 30544501, 2018). "CAFs produce higher levels of tumor-promoting factors, such as HGF, FGF, TGFβ, PDGF, VEGF, and EGF, as compared to normal fibroblast; these factors act in a paracrine manner on the cognate receptors expressed on adjacent tumor cells." (PMID 30544501, 2018). "Overall, MET and HGF concur to increase neovascularization, tumor expansion, and the release of neoplastic emboli into the bloodstream, regardless of the state of MET activation in cancer cells." (PMID 30544501, 2018). "The mechanisms of c-Met/HGF signaling in regulating tumor growth and metastasis involve many aspects, including proliferation, angiogenesis in primary tumors, stimulating motility to form micrometastases, and branching morphogenesis." (PMID 28475121, 2017). "Both YB-1 and MACC1 regulate the HGF/c-Met signaling pathway and induce tumor invasion and metastasis in several cancer types." (PMID 28624808, 2017). "To determine the effect of HGF on tumor metabolism, we compared the expression of glucose transporters in WT and hHGF KI SCID mice subjected to anti-angiogenic therapy." (PMID 28445144, 2017). "Here we focus on HGF/c-Met impact on cellular signaling in HNSCC to potentiate tumor growth and disrupt therapeutic efficacy." (PMID 29231907, 2017). "In the tumor microenvironment, growth factors and cytokines, such as hepatocyte growth factor (HGF) and epidermal growth factor (EGF), are frequently secreted from tumor cells and/or tumor-associated stromal and inflammatory cells." (PMID 28587113, 2017). "Targeted deletion of IKKβ in fibroblasts which increased HGF expression, triggered increased proliferation of intestinal epithelial cells and enhanced inflammation-induced tumor formation in IKKβ mutant mice." (PMID 28420162, 2017). "The VEGF/VEGFR and the HGF/cMET pathways are key mediators of the interplay of tumor cells and their microenvironment." (PMID 29228696, 2017). "Mice were then treated with the BRAF inhibitor C-1 (10 mg/kg, QD, by mouth [PO]) or vehicle and tumor growth was monitored to characterize HGF-mediated rescue." (PMID 28147313, 2017). "Hepatocyte growth factor (HGF) was first discovered in mouse liver and has been found to be linked with tumour development." (PMID 28393839, 2017). "Neutrophils, as a type of inflammatory cells, are considered to be involved in different steps of tumor development through the production of a variety of cytokines, such as oncostatin M, hepatocyte growth factor, and transforming growth factor- (TGF-) β." (PMID 28321405, 2017). "Pharmacological inhibition of GLUT1 in the presence of glucose killed tumor cells as effectively as glucose deprivation, and this effect was antagonized by HGF." (PMID 28445144, 2017). "In other cancer entities such as gastric and colon cancer, HGF/c-Met signaling was shown to be operative in fibroblasts within the tumor microenvironment, thereby contributing to tumor progression." (PMID 28212658, 2017). "It is widely accepted that hepatocyte growth factor (HGF) is involved in tumor migration and invasion, and EGCG has the capacity to suppress its activity." (PMID 28884125, 2017).
tumor (continued). "As some of these physiological processes are important for tumor growth and metastasis, c-Met/HGF signaling has been identified as playing important roles in many human cancers." (PMID 28475121, 2017). "The trypsin-like serine proteases, matriptase, hepsin and HGF activator (HGFA), which are commonly over-expressed in tumor cells, are three principal proteases responsible for HGF activation." (PMID 28420162, 2017). "The silencing of HIF-1β expression suppressed tumor cell growth and inhibited the expression of tumor growth-related factors, such as vascular endothelial growth factor, epidermal growth factor, and hepatocyte growth factor." (PMID 28053598, 2017). "As is expected, liver HGF is significantly upregulated with the implantation of tumour; multi-point injection of lenti-virus containing HGF shRNA significantly suppressed HGF expression in the liver." (PMID 28393839, 2017). "HGF/SF mice also exhibit spontaneous neoplasms of both mesenchymal and epithelial cell origins, a profile likely determined by MT promoter activity across diverse cell types." (PMID 28788083, 2017). "Effect of HGF inhibition was equivalent to gemcitabine in reduction of tumor volume but had a significantly greater effect on reducing metastasis." (PMID 29100344, 2017). "Immunohistochemistry analysis also revealed that IRCR201 significantly inhibited the proliferation of tumor cells and angiogenesis of tumor-associated blood vessels, suggesting that IRCR201 suppresses the HGF/c-Met pathway in the tumor microenvironment." (PMID 28902178, 2017). "MET/HGF mutations and overexpression are present in a high percentage of GBM tumors and previous studies have demonstrated that inhibition of MET in tumor cells leads to growth inhibition, tumor regression and decreased metastatic potential." (PMID 28696366, 2017). "As HGF is known to have an angiogenic effect in several other cancers, tumor sections were stained for the endothelial cell marker CD31, an indicator of neo-angiogenesis." (PMID 29100344, 2017). "The protein product of SPINT2 inhibits HGF activator, which prevents the formation of active hepatocyte growth factor, has been taken as a putative tumor suppressor." (PMID 28086821, 2017). "This contradicts a previous study in which elevated serum HGF levels were proposed as a biomarker for tumor progression and suggested to enhance angiogenesis and tumor cell invasion." (PMID 28522899, 2017). "In qualitative terms, Met3 and Met5 had comparable results of PC-3 tumors (human prostate cancer with high expression of c-MET) and SK-LMS-1/HGF tumors in mice models with high tumor/whole body ratio." (PMID 28485003, 2017). "In contrast, with the more complex HGF treated tumor cell population comprised of 89% EGFRL858R, 10% EGFRL858RBRAFV600E, 1% EGFRL858R, T790M, only combination strategies with switching horizons of 10 day or shorter induced a response." (PMID 28287179, 2017). "Development of these HGF SCID models was pivotal in the advancement of in vivo investigations of HGF/c-Met signaling enabling enhanced tumor growth of HGF-dependent cell lines and more translatable investigation of the pathway in HNSCC." (PMID 28441771, 2017). "Antibody 7A2/107_A07 inhibited HGF/SF-induced cell migration and DNA synthesis in vitro, endothelial cell tubulogenesis in a co-culture assay and tumor growth in vivo in a xenograft model." (PMID 28827556, 2017). "The anti-HGF DARPin® molecule had little discernible effect on tumor blood vessels but MP0250 gave a marked reduction in the number of vessels and the vessels present appeared to have no lumen." (PMID 29228696, 2017). "The antibody, 107_A07, inhibited HGF/SF-induced cell migration and proliferation in vitro and inhibited growth of tumor xenografts in vivo." (PMID 28827556, 2017).
tumor (continued). "A candidate factor that has received some attention in recent years is the hepatocyte growth factor (HGF), which has been shown to have a role in the progression of PC, particularly with respect to stromal-tumor interactions." (PMID 29100344, 2017). "IRCR201 exhibits tumor growth inhibitory activity in various cancer types harboring HGF-dependent or HGF-independent/c-Met-amplified activation." (PMID 28902178, 2017). "In previous clinical studies, the serum HGF level correlated positively with the tumor metastasis of HCC." (PMID 28587113, 2017). "Engineered proteins mimicking the IPT domains of Met show anti-tumor effects in mice; in vitro display inhibit HGF induced cell growth and invasion." (PMID 29231907, 2017). "The antitumor activity of cabozantinib was also investigated in HCCs, which inhibits the migration and invasion of tumor cells by blocking the HGF- mediated MET signaling." (PMID 28903454, 2017). "Several circulating cytokines, including hepatocyte growth factor (HGF), TGF-beta, CXCL8 and CXCL12, have been implicated as contributors to anoikis signaling in some kinds of tumor cells." (PMID 28430645, 2017). "This suggests that an oxidative microenvironment is a contributing factor in regulating HGF-c-Met-mediated tumor stroma co-evolution." (PMID 29296173, 2017). "Our in vivo study further showed that scavenging ROS with EcSOD in MDA-MB231 significantly inhibited HGF-mediated tumor growth in mice." (PMID 29296173, 2017). "Among the metastatic factors in the tumor microenvironment, hepatocyte growth factor (HGF) has been well known to play critical roles in tumor progression, including HCC." (PMID 28587113, 2017). "Due to its role in tumor progression and therapeutic resistance, both HGF and MET have emerged as valid therapeutic targets." (PMID 28420162, 2017). "First, neutrophils, as a type of inflammatory cells, are involved in different steps of tumor development through the production of a variety of cytokines, such as oncostatin M, interleukin-6, hepatocyte growth factor, and tumor necrosis factor." (PMID 29029493, 2017). "Significant differences of IL-1β, IL-6, TNF-α and HGF were also detected in the comparison between tumor and non tumor HF and LF-HC bearing mice." (PMID 28881825, 2017). "The effect of HGF inhibition thus only reflects effects on functions of the HGF/cMET pathway in the tumor stroma if the implanted human tumor cells express human HGF which produces autocrine activation of cMET expressed by the cells." (PMID 29228696, 2017). "To access the in vivo effects of liver HGF on the formation and growth of liver metastases, we subsequently established mouse tumour model." (PMID 28393839, 2017). "Recently, the role of endosomal signaling in tumor progression triggered by metastatic growth factors, including HGF, has been highlighted." (PMID 28587113, 2017). "Given that the HGF/c-MET pathway is involved in multiple stages of HNSCC tumor progression, it is a highly promising therapeutic target for this disease." (PMID 28441771, 2017). "Fibroblasts are the predominant constituent of the tumor stroma and Hepatocyte Growth Factor (HGF), the specific ligand for the tyrosine kinase receptor c-MET, is a major component of their secretome." (PMID 28420162, 2017). "HGF is a key growth factor in the tumor micro-environment that inhibits the response of cancer cells to targeted therapy." (PMID 28968967, 2017). "MET, the receptor for HGF, can be activated to promote migration and invasion of tumor cells and provides a potential target for treating HCC." (PMID 28903454, 2017). "With ample evidence for the role of the c-Met/HGF pathway promoting tumor progression, various c-Met inhibitors are under active investigation in a variety of cancers, including HNSCC." (PMID 29348891, 2017). "The therapeutic strategy aiming at HGF-c-Met signaling for the prevention of tumor progression of HCC was intensively investigated decades ago." (PMID 28587113, 2017).
tumor (continued). "Next, inhibition of proliferation of the HGF-autocrine tumor cell line U87MG was determined in vitro." (PMID 29228696, 2017). "LEF1 serves as a transcriptional effector of the Wnt/β-catenin pathway and is critical for the tumor invasion induced by hepatocyte growth factor (HGF)." (PMID 28934958, 2017). "Activation of the HGF/c-MET pathway has been evaluated using serum or plasma HGF, because HGF is expelled from tumor cells to the extracellular matrix and blood plasma by a paracrine mechanism." (PMID 29069748, 2017). "HGF has been identified as a factor in the tumor microenvironment that blocks the response to cancer therapy." (PMID 28420162, 2017). "A recent study has indicated that an HGF-regulated tyrosine kinase substrate harboring tumor suppressive activity is regulated by HGF stimulation." (PMID 29133945, 2017). "FGF2, HGF and EGF are associated with the angiogenesis, growth, proliferation and differentiation of numerous cell types, including certain tumor cells." (PMID 28486560, 2017). "We demonstrated that novel inhibitors of pro-HGF processing block crosstalk between tumor cells and fibroblasts and thus restrain the tumor-promoting activity of fibroblasts." (PMID 28968967, 2017). "Factors in the tumor microenvironment, including HGF, promote tumor heterogeneity, at least in part, by providing an appropriate niche for cancer stem cells (CSC)." (PMID 28420162, 2017). "Given the critical roles of the MET/HGF pathway in tumor growth and development, various groups developed MET blocking antibodies." (PMID 28406969, 2017). "Cancer-associated stroma secretes a plethora of factors such as HGF, IL-6, TGF-β to promote the growth and invasion of the underlying tumor." (PMID 28186964, 2017). "When combined with HGF inhibition, the antimetastatic, antiangiogenic and antiproliferative effects were reduced and there have even been cases of tumor progression." (PMID 29254283, 2017). "Overall, our study indicates a contributing role of an oxidative tumor microenvironment in promoting an activated-phenotype of fibroblasts in addition to supporting HGF/c-Met signaling during cancer-fibroblast interactions." (PMID 29296173, 2017). "Although HGF has been reported to be upregulated in various types of cancer, the expression pattern of HGF in tumour metastases is little known." (PMID 28393839, 2017). "Elevated HGF levels from autocrine (tumor cell), paracrine (stromal), or systemic production were proposed to represent a novel mechanism of vemurafenib resistance." (PMID 28147313, 2017). "We demonstrated that HGF, commonly overexpressed in the tumor microenvironment, confers resistance to MET- targeted therapy in MET-amplified NSCLC cells." (PMID 28968967, 2017). "Elevated c-Met expression in tumor cells also leads to enhanced c-Met activity within the tumor tissue, since profound HGF expression within the tumor stroma activates c-Met on cancer cells in a paracrine manner." (PMID 28212658, 2017). "Hyperactivity of the HGF/c-Met and PDGF/PDGFR signaling pathways occur in different cancer types and have been associated with the uncontrolled growth of tumor cells, epithelial-to-mesenchymal transition, invasiveness, and metastasis." (PMID 28989976, 2017). "HGF, which is commonly overexpressed in the tumor microenvironment, is a frequent source of resistance to targeted therapy." (PMID 28968967, 2017). "Since tumor stroma cells, such as activated fibroblasts are the predominant source of HGF, we determined if EcSOD will affect the cancer cell-fibroblast interactions in the context of HGF stimulation." (PMID 29296173, 2017). "Tumor cells that had adapted through therapy exhibited elevated HGF expression and the c-MET inhibitor crizotinib enhanced AR42 pazopanib lethality in this evolved drug-resistant population." (PMID 28146421, 2017).
tumor (continued). "MET tyrosine kinase plays an integral role in carcinogenesis by promoting tumor invasion, protection from apoptosis, and angiogenesis; binding to HGF or scatter factor activates MET." (PMID 28077782, 2017). "We demonstrated that SRI31215, an inhibitor of pro-HGF activation, blocked crosstalk between tumor cells and fibroblasts in MET-amplified NSCLC cells." (PMID 28420162, 2017). "TANs recruited by tumor then release pro-growth and pro-invasion factors including hepatocyte growth factor (HGF), reactive oxygen species (ROS), reactive nitrogen species (RNS), neutrophil elastase (NE), neutrophil collagenase (MMP8), and gelatinase B (MMP9)." (PMID 28223716, 2017). "The HGF/c-MET signal pathway plays a significant role in tumor development and metastasis, often through activation of downstream molecules, including AKT and ERK1/2 pathways." (PMID 28404966, 2017). "Because HGF is frequently overexpressed in the tumor microenvironment, our work highlights the need to include inhibitors of biological activity of HGF into therapeutic regimen in MET-amplified NSCLC patients." (PMID 28968967, 2017). "Confirming our previously published results, HGF inhibition was as effective as gemcitabine in reducing tumor volumes in our model." (PMID 29100344, 2017). "Activated c-Met in normal cells – predominantly in stromal cells including MSC - plays a major role in organogenesis and wound healing whereas in tumor cells, HGF-activated c-Met contributes to invasive and metastatic behavior." (PMID 28212658, 2017). "Binding of HGF to its MET receptor triggers a series of intracellular signaling events leading to tumor cell proliferation, survival invasion and angiogenesis." (PMID 26637806, 2016). "mAb m224G11 suppressed U87MG tumor growth demonstrating single agent activity against this HGF-dependent tumor." (PMID 26879245, 2016). "It is activated by its ligand HGF, thus playing an important role as a dominant oncogene in tumor development and progression." (PMID 27813498, 2016). "High stromal HGF was found in 51% (110/228) of the tumours and high cytoplasmic staining in 49% (105/228)." (PMID 27175600, 2016). "Some of the growth factors implicated in tumor vascularization include vascular endothelial growth factor (VEGF), placental growth factor (PlGF), fibroblast growth factor (FGF) and hepatocyte growth factor (HGF)." (PMID 27626690, 2016). "Resistance to targeted therapy can also originate from the tumor microenvironment where fibroblasts are a common source of pro-HGF." (PMID 27121052, 2016). "The tumor cells will release cytokines such SDF-1 and HGF to stimulate angiogenesis to support tumor growth." (PMID 27965712, 2016). "This belief originated from experiments in which forced expression of a SULF in several tumor lines caused reduced growth-factor signaling by HB-EGF, FGF-2 or HGF, and diminished tumorigenicity." (PMID 26882224, 2016). "Many tumor types, including gastric, colorectal, renal, breast, pancreatic, lung, thyroid, and hepatocellular carcinoma, have aberrant activation of the HGF/MET signaling pathway." (PMID 27422720, 2016). "The stronger HER2 expression of tumor tissues became, the higher serum level of HGF were detected in patients who received first-line chemotherapy (p = 0.027, Kruskal Wallis test)." (PMID 26716644, 2016). "In situ hybridization and immunohistochemical staining were used to investigate expression levels of miRNA-200a and HGF in 134 formalin-fixed paraffin-embedded tumor specimens from clinical stage I -IIIA NSCLC, respectively." (PMID 27374174, 2016). "We previously reported that high fat diet (HFD) elevated HGF, cMET, and phospho-cMET in normal mammary gland, with accelerated tumor development, compared to low fat diet (LFD)-fed lean controls in a murine model of BBC." (PMID 27057482, 2016). "The same pattern was seen in cohort 1 amongst patients whose tumours harboured more than two HGF copies and/or high expression of cytoplasmic HGF." (PMID 27175600, 2016).